YAP1 (Yes1 associated transcriptional regulator)
Diseases named in the same sentence as YAP1 in open-access papers (continued):
Sharing a sentence is not in itself a finding about the gene and the disease.
tumor (continued). "Furthermore, TEAD2, a TF that plays a key role in the Hippo signalling pathway by interacting with YAP1, was predicted to bind and regulate four lincRNAs (LINC00261, RP11-161M6.2, GMDS-AS1, MIRLET7BHG), three of them showing the strongest decrease in basal-like tumours." (PMID 32727085, 2020). "However, the tumor suppressive role of YAP1 is not detected in our materials of NSCLC." (PMID 29163769, 2017). "Moreover, the expression of LATS2 and p-YAP1(Ser127) increased, whereas YAP1, Axl, c-Myc, Cyr61, MMP-2 and MMP-9 expression levels were simultaneously decreased in amlexanox-treated group relative to the DMSO-treated group, which was consistent with the subcutaneous tumor tissues results." (PMID 29048430, 2017). "Altogether, these data showed that YAP1 expression in the primary tumour is low despite invasive potential of the cells, and suggested that YAP1/TAZ signalling could be activated by biophysical cues present in the lymphatics and/or lymph nodes to contribute to high YAP1 expression in metastases." (PMID 28098159, 2017). "In addition, MKN-45 GC cells induced tumor formation despite having no YAP1 expression." (PMID 27835600, 2016). "However, the present study suggests for the first time that YAP1 overexpression could promote tumor growth but do not affect tumorigenesis." (PMID 27835600, 2016). "Immunohistochemical staining of tissue samples confirmed high expression levels of PP1γ, YAP1, SOX2, and NANOG proteins in tumor tissues compared to adjacent non-cancerous tissues." (PMID 40626009, 2025). "Distinct from typical oncogenes, YAP1 and WWTR1 do not independently initiate spontaneous cancer development, though they are indispensable for tumor progression." (PMID 40919137, 2025). "In silico analysis also revealed a negative correlation between p63 and YAP1 expression levels in ADC and SCC tumor samples." (PMID 40603978, 2025). "Since the reconstitution of YAP1 could not completely restore the malignant phenotypes caused by the inhibition of CDK4/6 in HCC cells, it is noteworthy that we cannot rule out the possibility of additional mechanisms involved in CDK4/6-mediated tumor progression of HCC." (PMID 40307228, 2025). "Further, inhibiting Yap1 or Cox2 singly does not make PDAC vulnerable to Gem-treatment, indicating that targeting cancer cells only or tumor stroma alone is insufficient to blackout the chemo-induced symbiotic signaling (left)." (PMID 39468013, 2024). "SMARCA4 expression was positively correlated with multiple NE genes including SYP, CHGA, INSM1, DLL3 and NCAM1 and negatively correlated with non-NE factors REST, NOTCH2, and YAP1 in both SCLC cell lines and patient tumor databases." (PMID 39080761, 2024). "IHC of continuous sections obtained from the same patient's cancerous and non-cancerous tissues revealed that CPNE3, YAP1, CYR61, and RAD51 were significantly positive in the tumor tissue and negative in the non-cancerous tissue." (PMID 38493426, 2024). "Consistently, the tumor growth and metastatic potentials of ID8 Cxcr1/2 CRISPRi cells with GFP/Luc were remarkably reduced in the WT mice as well as the Yap1+/− and Yap1−/− mice without any apparent change in survival and body weight." (PMID 36624516, 2023). "The expression of tumor‐derived Vimentin (VIM) was nearly restricted to triple‐negative SCLC tumors (15/19, 78.9%) while YAP1 expression was distributed widely in other subtypes." (PMID 37789961, 2023). "Our studies identify the Hippo effector, YAP1, as a target of CIC potentially through non-consensus GGAA repeat sites and demonstrate that CIC and YAP cooperate to control drug resistance and tumor progression in human cancer." (PMID 36198276, 2022). "In present study, we identified the Hippo pathway effector YAP1 as the key downstream target of LIN28 to induce the CSC-like properties, tumor growth and metastasis in TNBC, which is independent of Let-7." (PMID 35102250, 2022).
tumor (continued). "In an in vitro cell model or in vivo tumor tissues, dipyridamole treatment resulted in a decline in the levels of HMGB1, RAGE, β-catenin, Runx2, YAP1, phosphorylated Smad2/3, and cyclin D1, but not TLR2 and TLR4." (PMID 33669632, 2021). "Double immunofluorescence staining for CBX4 and YAP1 expression in Huh7-SR tumours with or without treatment with their inhibitors was also conducted, and the expression of CBX4 and YAP1 was as prominent in the nucleus as it was in the cytoplasm in SR tumours." (PMID 33473171, 2021). "We previously reported that NF2 knockdown or forced YAP1 or TAZ expression in HOMC cell lines resulted in tumorigenicity in subcutaneously transplanted immunodeficient mice, while no tumor formation was detected when merely transplanting HOMC cell lines." (PMID 34663305, 2021). "A prognostic role of YAP1 expression was observed in subsets of both ERG positive and ERG negative cancers, althougth stronger in ERG negative tumours." (PMID 32488048, 2020). "Gene expression analysis of lung and breast cancers has recently provided insight as, in addition to YAP1 activation, embryonic stem cell (ESC) signatures are significantly elevated in human tumours lacking RASSF1A." (PMID 31268606, 2019). "Differences in the mRNA expression of NMU and YAP1 between tumor and non-tumor tissues were identified using four GEO databases, which showed that NMU and YAP1 mRNA expression levels were significantly higher in tumor than in non-tumor tissues." (PMID 31575084, 2019). "Both in-frame fusions from advanced disease, ESR1-e6>YAP1 and ESR1-e6>PCDH11X, promoted estrogen-independent growth (−E2), but the primary tumor fusion event, ESR1-e6>NOP2, had no growth-promoting properties." (PMID 30089255, 2018). "We successfully established the xenograft tumor models using MKN-45 GC cells, but immunochemistry showed that there was no YAP1 expression in MKN-45 cells." (PMID 27835600, 2016). "As YAP1 knockdown significantly decreased proliferation in MCF-7 cells, the negative result in tumour formation was perhaps expected." (PMID 24559095, 2014). "However, Dnmt1 re-expression in Sox9 CKO livers slightly but significantly restored tumor formation driven by Akt-NRAS, but not Akt-YAP1, implying the partial involvement of Dnmt1 in Akt-NRAS tumor development under the SOX9." (PMID 39273023, 2024). "We observed in tumour samples that AURKA inhibition does not influence the expression and phosphorylation levels of LATS-1 and MOB-1, main effectors of the Hippo-dependent YAP1 phosphorylation at Ser397." (PMID 38467828, 2024). "However, the current research does not involve the relationship between YAP1 and NKT cells, γ δ T cells or B cells in tumor immunity of HCC." (PMID 38550587, 2024). "Furthermore, we evaluated expression of GRK3, YAP1, and SOX9 and cell proliferation marker Ki67 in the tumor tissues of mice treated with or without LD2 using IF." (PMID 35996148, 2022). "Moreover, YAP1 has the capability to reprogram the non-CSCs into cells that have CSC-like features and to keep the stemness of tumor cells through the induction of autophagy." (PMID 31963556, 2020). "In prior studies, concurrent KMT2A and YAP1 rearrangements were noted in only one tumor tested by both break-apart fluorescence in situ hybridization (FISH) probes; negative FISH results for KMT2A and/or YAP1 were common in cases where the fusion was confirmed by sequencing." (PMID 32461620, 2020). "However, 6 of 9 cores with strong RB1 staining demonstrated little to no YAP1 expression (see core SC8) and the vast majority of tumor cores were negative for RB1 and YAP1 staining, which mirrors our observations in SCLC cell lines." (PMID 29088741, 2017). "Analyzing the percentage of apoptotic cells via flow cytometry revealed that YAP1-depleted HEYA8 and OVCAR8 cells did not respond to platelets and showed the same apoptosis rate as the respective controls in which detached tumor cells were grown without platelets." (PMID 28827520, 2017).
tumor (continued). "The ERK activation status, on the other hand, did not correlate with proliferation in autochthonous tumours, xenografts, or cultured cells, implying that in the absence of RAF1 proliferative signalling is rewired to rely on the activation of YAP1 and STAT3 rather than ERK." (PMID 28000790, 2016). "However, Snail1 expression is only slightly higher in CRC tumor specimens than paired normal tissues (data not shown), suggesting that DUB3 might promote CRC progression primarily by stabilizing YAP1 rather than Snail1." (PMID 39968498, 2025). "Furthermore, YAP/TAZ may overall be tumor suppressors in SCLC67, which makes it unclear whether YAP1+ non-NE cells should be targeted or not." (PMID 35577801, 2022). "Interestingly, YAP1 KO CD4 and CD8+ T cells demonstrated superior tumor infiltration compared to wild-type counterparts, and tumor growth was either greatly delayed or nearly absent in tumor-bearing CD4–Cre or Foxp3–Cre mice." (PMID 34685695, 2021). "Electroporation of YAP1-MAMLD1(L103P) did not attenuate the YAP1-MAMLD1-mediated tumor formation (n = 5/5, median survival: 31.5 days), suggesting that MAMLD1 transactivation function for Notch signaling may not be relevant to the YAP1-MAMLD1 oncogenic capacity." (PMID 31477715, 2019). "Although we do not discuss the relationship between YAP1 and glycolysis in detail here, our findings and recent studies suggest that YAP1 promotes the transcription of HIF1A in cancer, indicating that LPA could affect tumor glycolysis through multiple upstream pathways." (PMID 37990271, 2023).
cancer (781 papers, 2008 to 2026). A tumor composed of atypical neoplastic, often pleomorphic cells that invade other tissues. "Previous studies have suggested that YAP1 regulates the transcriptional expression of cytoskeletal regulators in cancer-associated fibroblasts to promote cancer cell invasion, matrix stiffening and angiogenesis." (PMID 41513610, 2026). "Dysregulation of this pathway, such as the overactivation of YAP1, is implicated in various diseases, particularly cancer." (PMID 40784457, 2025). "Several cancers are associated with YAP1 dysregulation, including liver cancer, breast cancer, and cervical cancer." (PMID 40603978, 2025). "To visually encapsulate this complexity, we have redesigned our schematic model to map YAP1-associated mechanisms across major cancer types, emphasizing tissue-specific pathways and therapeutic vulnerabilities." (PMID 40977060, 2025). "In contrast, reducing KDELR1 levels increased YAP1 phosphorylation, causing YAP1 to accumulate in the cytoplasm in an inactive state, thereby suppressing cancer cell growth and improving drug sensitivity." (PMID 41294677, 2025). "Target genes of these transcription factors include those involved in proliferation (CCND1, CCND2, CCND3, MYC), EMT (TWIST2, CDH2), and migration (CTGF, CYR61), and hence YAP1/TAZ overactivation has been implicated in the progression of various cancer types." (PMID 40301543, 2025). "The interplay between the p63 isoform (ΔNp63), microRNA-141-3p (miR-141-3p), and Yes-associated protein 1 (YAP1) has emerged as a potential area of interest in cancer progression." (PMID 40603978, 2025). "The activation of YAP1 must be tightly controlled, as its dysregulation is implicated in various diseases, including cancer, cardiovascular diseases, neurological disorders, and immune dysfunction." (PMID 40784457, 2025). "Numerous studies have linked elevated expression and activity of YAP1 to poor patient outcomes in various cancers, including HCC." (PMID 40307228, 2025). "Aberrant activation of YAP1 has been implicated in the initiation and progression of various cancers, including lung, mesothelioma, gastric, and colorectal cancers, where it is associated with poor prognosis and resistance to targeted therapies." (PMID 40731926, 2025). "We also investigated the effect of DUB3 cancer-related mutations on the ubiquitination and turnover of YAP1." (PMID 39827153, 2025). "The Yes‐associated protein 1 (YAP1) is frequently dysregulated in cancers, contributing to cancer stemness, chemoresistance, and cancer‐related death." (PMID 39968498, 2025). "High YAP1 expression is negatively associated with the infiltration of activated NK cells in pan-cancer analyses." (PMID 41028521, 2025). "These genes have been closely linked to cancer cell mechanoadaptability during the metastatic cascade with YAP1 inhibition leading to reduced cell stiffness in response to fluid shear stress and reduced migration and extravasation." (PMID 41028875, 2025). "It is worth noting that whereas VGLL3 seems to be enriched in the skin of women and is associated with female-biased autoimmune diseases, YAP1 is associated with pro-oncogenic signaling, and the incidence of cancer is higher in men." (PMID 40741215, 2025). "YAP1 amplification is prevalent in cancers and is linked to cancer‐cell maintenance, cellular invasion, chemoresistance, hyperproliferation and metastasis." (PMID 38659080, 2024). "It was found that YAP1 substitutes for the loss of oncogenic KRAS in human cancers and that YAP1 expression is required for KRAS-induced cell transformation." (PMID 39456549, 2024). "Regarding YAP1, reminiscent of previous findings in cancer cells, this was in addition linked to an increase in phosphorylation of YAP1 at Ser127, which induces its cytoplasmic sequestration and degradation." (PMID 38830870, 2024). "The Yap1-Cox2 signaling also seems to be generally associated with adaptive chemo-resistance in other cancers." (PMID 39468013, 2024).
cancer (continued). "YAP1 stimulated the production of genes encoding secretory factors that supported neoplastic proliferation and cancer progression." (PMID 38730733, 2024). "KEGG enrichment analysis of the top 300 downregulated genes revealed that proteoglycans in cancer, regulation of actin cytoskeleton, and focal adhesion are the most affected pathways in CAFs after the loss of YAP1 expression." (PMID 38308096, 2024). "The elevated expression of BRD2/BRD3/BRD4/YAP1 is a risk factor from the Cox cross-pan-cancer dataset proportional hazards model in a variety of tumors, including SKCM, besides, there was an association between BRD4 and YAP1." (PMID 38169595, 2024). "Ectopic overproduction of MST1 or MST2 in cell lines promotes apoptosis (12, –, 16), and elevated YAP1 protein levels are associated with human cancers, suggesting that MST1/2 possess pro-apoptotic activities to limit cell proliferation and tumors." (PMID 38624208, 2024). "A significant proportion of cancer patients carried the fusion- and frame-related mutations in YAP1 and TEAD2, respectively." (PMID 39572544, 2024). "We found that YAP1 attenuation results in downregulation of several CXCR2-associated ligands in cancer cells and in xenograft tumors." (PMID 39630608, 2024). "The YAP1/Hippo signaling pathway is a key regulator of organ size and tissue homeostasis, and its dysregulated expression is associated with cancer pathogenesis." (PMID 39345743, 2024). "Platelets have been shown to help cancer cells evade anoikis by activating yes-associated protein 1 (YAP1) signaling." (PMID 39190751, 2024). "Paradoxically, bioinformatic analysis found that YAP1 was negatively associated with apoptosis, possibly because the TCGA database was based on data from cancer studies." (PMID 39308919, 2024). "YAP1-signalling pathway is associated with various hallmarks of oncogenesis in many cancer types, included HGSOC133–136." (PMID 38346978, 2024). "Another recent study showed YAP1-dependent proliferative loss in YAP1-silenced cancers, but this effect remains poorly studied in NE cancers other than SCLC." (PMID 36719743, 2023). "Previous studies have proved that myosin and Src functions are required to maintain YAP1 activation in cancer-associated fibroblasts, and Src is also an upstream activator of YAP1 in CRC." (PMID 37031206, 2023). "FGB is a glycoprotein that is involved in blood clotting, and Hippo/YAP1, a regulator of cellular processes including proliferation, apoptosis, and differentiation, have both been implicated in cancer development and progression." (PMID 37953225, 2023). "YAP1 is a transcriptional coactivator of the Hippo signaling pathway and has been implicated in the development and progression of various types of cancer, making it a potential therapeutic target." (PMID 37147639, 2023). "MKLN1-AS oncogenic involvement in cancer is linked to YAP1,and MKLN1-AS can increase HCC development by inducing YAP1 expression." (PMID 37647290, 2023). "Significant inhibition of BRD4 resulted in the depletion of YAP1 and loss of cancer stem cell-like properties." (PMID 36674511, 2023). "We also demonstrate that several core EMT-regulating transcription factors (EMT-TFs) are upregulated in cancer cells during direct contact with fibroblasts, as is Yes-associated protein (YAP1), a major regulator of the Hippo pathway." (PMID 36936987, 2023). "In these cancers, YAP1 and WWTR1 expression is associated with increased drug resistance, metastasis, and poor outcomes." (PMID 36719743, 2023). "Dysregulation of the Hippo pathway, including the overexpression or loss of the transcriptional co-activator Yes-associated protein 1 (YAP-1), has been linked to the development of cancer." (PMID 37476371, 2023). "Conversion of normal fibroblasts into cancer-associated fibroblasts is modulated by YAP1-mediated activation of SRC, which stimulates cytoskeletal protein activation and actomyosin contractility." (PMID 37120696, 2023).